VGF (VGF nerve growth factor inducible)
Diseases named in the same sentence as VGF in open-access papers (continued):
Sharing a sentence is not in itself a finding about the gene and the disease.
neurodegenerative disease (11 papers, 2017 to 2025). A disorder of the central nervous system characterized by gradual and progressive loss of neural tissue and neurologic function. "This makes VGF not only a promising biomarker for neurodegenerative diseases, but also a prospective target for therapy." (PMID 40082954, 2025). "Publications that assessed the level of VGF and/or its derived peptides among people with neurodegenerative diseases and compared them with healthy people were included." (PMID 36619561, 2022). "VGF is increasingly recognized as a major player in neurodegenerative diseases." (PMID 40082954, 2025). "Recently, VGF and its peptides have been highlighted in neurodegenerative diseases." (PMID 36619561, 2022). "One example, VGF, has been widely studied in several neurodegenerative diseases." (PMID 32192109, 2020). "In the rat brain, VGF is expressed in areas involved in the regulation of feeding, reproduction, stress responsiveness and general homeostasis, and VGF-derived peptides have been found significantly decreased in some neurodegenerative diseases." (PMID 28424618, 2017).
psychiatric disorder (11 papers, 2011 to 2025). A disorder characterized by behavioral and/or psychological abnormalities, often accompanied by physical symptoms. "In this network, BDNF and NGF are upstream of VGF and highly associated with psychiatric disorders and neurogenesis." (PMID 27877109, 2016). "Another protein that showed increased expression is VGF, which has been shown to be a biomarker and target for neurodegenerative and psychiatric disorders." (PMID 38577622, 2024). "On the whole, these studies suggest a positive role of VGF in neurogenesis and connections of VGF in psychiatric disorders." (PMID 27877109, 2016). "The findings in this study indicate a correlation between NPAS3 and VGF, and propose a potential network composed by NPAS3, VGF and several other pivotal factors relevant to neurogenesis and psychiatric disorders." (PMID 27877109, 2016). "This network collectively detailed how NPAS3 connects with VGF and intersected neural cell proliferation, synaptic activity and psychiatric disorders." (PMID 27877109, 2016). "VGF is a neurosecretory peptide that is processed into at least 12 VGF-derived peptides that have roles in neurogenesis, synaptogenesis, and learning and memory; VGF has been found to be dysregulated in multiple neurodegenerative and psychiatric disorders." (PMID 39858627, 2025). "Until know, data suggest dysregulation of VGF in psychiatric disorders." (PMID 22654714, 2011). "Therefore, NPAS3 and VGF might function to orchestrate the molecular response during the processes of neurogenesis and psychiatric disorders." (PMID 27877109, 2016). "Thus, it became clear that somehow the neurotrophin-inducible neuropeptide VGF has a role and may constitute a target in the treatment of some psychiatric disorders." (PMID 22654714, 2011). "However, the mechanism whereby VGF upregulation contributes to mental illness is unknown." (PMID 28680036, 2017). "Revealing the regulation of NPAS3 on VGF and the precise mechanism of how NPAS3 influences neural cell proliferation will increase our understanding of pathophysiological mechanisms of psychiatric disorders." (PMID 27877109, 2016). "Neuronal PAS domain protein 3 (NPAS3) and VGF (VGF Nerve Growth Factor (NGF) Inducible) are important for neurogenesis and psychiatric disorders." (PMID 27877109, 2016). "All these studies highlight the importance of neurosecretory protein VGF and TTR in neurological/psychiatric disorders." (PMID 25256248, 2015). "The neurosecretory protein VGF (non-acronymic) has emerged in large-scale -omics studies as a potential biomarker of several neurodegenerative and psychiatric diseases." (PMID 40082954, 2025). "The psychiatric disorder-associated variants p.Val304Ile and p.Ala552Pro were found to be normally expressed and localized to the nucleus, and further, did not affect interaction with ARNT, nor regulation of the VGF reporter construct relative to wild-type." (PMID 30509165, 2018).
infection (4 papers, 2008 to 2024). The state of being infected such as from the introduction of a foreign agent such as serum, vaccine, antigenic substance or organism. "In the sera of M. fortis, the levels of IL-1b, IL-3, IL-4, IL-10, IL-17, MCP-1 and VGF were found to increase from the second to the third week post-infection." (PMID 28900150, 2017). "Previous studies had shown that VACV replicates more poorly in resting mouse 3T3 cells than actively growing cells and this was most severe in low multiplicity, multicycle infections with a mutant virus unable to express the secreted growth factor VGF." (PMID 19055736, 2008). "With wild type virus, secreted VGF could activate resting cells prior to the next round of infection." (PMID 19055736, 2008). "However, some ion channel genes (calcium channel or potassium channel) appeared to be down-regulated; and growth factors (EGF, EGR, VGF etc.)were also down; and eventually the transcription factors such as the elongation factors were also reduced during the OPPV infection." (PMID 26950733, 2016). "However, although the cytosolic VGF did not increase within 48 h, the secreted VGF increased in OSCC cells following infection at 48 h." (PMID 38528565, 2024).
nervous system diseases (4 papers, 2012 to 2025). "In addition, other genes upregulated after finasteride treatment in the hypothalamus, like VGF and IRF2BPL, are associated with neurological disorders." (PMID 38493246, 2024). "These modules included synaptic markers that already feature well-described decreases in neurodegeneration, such as VGF and NPTX2, reinforcing their potential as reliable markers of degeneration across different neurologic diseases." (PMID 39107789, 2024).
metabolic disorders (2 papers, 2016 to 2017). "TLQP-21 is one of many bioactive products derived from post-translational cleavage of the C-terminal region of VGF, a propeptide that could be involved in psychiatric, neurologic and metabolic disorders." (PMID 28424618, 2017).
head and neck tumors (1 paper, 2014). "VGF is also methylated in ovarian, testicular and head and neck tumors." (PMID 24927296, 2014).
VGF also shares sentences with these, for which no sentence is quoted: amyloid (3 papers); melanoma (3); breast tumors (2); colorectal cancer (2); Hyperglycemia (2); Hyperinsulinemia (2); Parkinson (2); peripheral nerve injury (2); psychosis (2); Acute encephalopathy (1); adenocarcinoma (1); adrenocortical carcinomas (1); arterial hypertension (1); Bladder Urothelial Carcinoma (1); brain disorder (1); cerebellar ataxia (1); cerebrovascular disease (1); cervical cancer (1); dementia with Lewy bodies (1); dyslipidemia (1); eating disorder (1); fibrosis (1); motor neuron degeneration (1); neuroendocrine carcinoma (1); neuroendocrine tumor (1); pancreatic cancer (1); protein misfolding disorders (1); pulmonary disease (1); pulmonary neuroendocrine tumors (1); relapsing-remitting MS (1).
A further 2 diseases each share a sentence with VGF in 1 paper.